PRDX4 (peroxiredoxin 4)
Diseases named in the same sentence as PRDX4 in open-access papers (continued):
Sharing a sentence is not in itself a finding about the gene and the disease.
glioblastoma (10 papers, 2012 to 2025). The most malignant astrocytic tumor (WHO grade IV). "PRDX4 gene knockdown in glioblastoma cells leads to increased sensitivity of the cells to ionizing radiation, suppression of growth, and metastasis formation." (PMID 30621289, 2019). "The PRDX4 gene and protein are also upregulated in human glioblastoma multiforme (GBM) and mouse models of this disease." (PMID 30558204, 2018). "PRDX4 has been described as having a tumor-promoting effect that is well-documented among various forms of cancer, including lung and renal cancer, leukemia, and glioblastoma." (PMID 39057065, 2024). "Aggressive radioresistant brain tumor species, glioblastoma, shows a high PRDX4 expression level." (PMID 30621289, 2019). "In supporting our novel finding on in vitro oxidative effects of 10 analogue, it was determined that most glioblastomas overexpressed ROS-degrading enzyme peroxiredoxin 4 (PRDX4) and suggested that pharmaceutical PRDX4 inactivation effectively kills the cancer cells by increasing ROS levels." (PMID 29890617, 2018).
glioma (10 papers, 2012 to 2024). A benign or malignant brain and spinal cord tumor that arises from glial cells (astrocytes, oligodendrocytes, ependymal cells). "It has been found that peroxiredoxin 4 (PRDX4) is upregulated in glioma stem cells (GSC) in the central region of the tumor, resulting in low levels of ROS production in GSC even in a hypoxic environment." (PMID 37173373, 2023). "It has also been revealed that ALDH1A1 and peroxiredoxin 4 are direct targets of β-catenin and contribute to glioma invasiveness." (PMID 36046036, 2022). "A proposed molecular mechanism of this phenomenon was the significantly upregulated expression of peroxiredoxin 4 (PRDX4) in glioma stem cells." (PMID 26682001, 2016). "Peroxiredoxin 4 (PRDX4), an ROS-reducing enzyme, facilitates the appropriate folding of proteins in ER and frequently upregulates proteins in high-grade glioma cells." (PMID 26188905, 2015). "Thus, the E-cadherin/β-catenin/ALDH1A1 and E-cadherin/β-catenin/peroxiredoxin-4 pathways are likely direct promoters of anoikis resistance in glioma." (PMID 36046036, 2022). "Piperlongumine, a natural plant product effectively inhibited PRDX4 in glioma cells." (PMID 26188905, 2015). "We next tested whether the GBM cell growth suppression upon Prdx4 knockdown was dependent on increased ROS level by employing an antioxidant N-acetyl cysteine (NAC) that can decrease ROS levels in glioma cells." (PMID 22916164, 2012). "In particular, overexpression of PRDX1, PRDX4, and PRDX6 has been reported in most histological glioma types compared to the normal tissues and correlated with poor survival of glioma patients." (PMID 38607010, 2024). "However, it was also reported that the KD reduced ROS levels in gliomas, accompanied by slowed tumor growth and changes in ROS modulating genes, including cyclooxygenase-2 (COX-2), glutathione peroxidase 7 (Gpx7) and peroxiredoxin 4 (Prdx4)." (PMID 36432618, 2022). "In addition, inactivation of peroxiredoxin 4, which comprises the TrxR system, by piperlongumine treatment was reported to exacerbate the intracellular ER stress, and the UPR pathway mediated the piperlongumine-induced apoptosis in glioma cells." (PMID 31105565, 2019).
type 2 diabetes mellitus (10 papers, 2011 to 2024). A type of diabetes mellitus that is characterized by insulin resistance or desensitization and increased blood glucose levels. "The glycine serine and threonine metabolism, maturity onset diabetes of the young, neuroactive ligand receptor interaction, propanoate metabolism, valine leucine and isoleucine degradation in control samples or high expression Prdx4 group." (PMID 38641608, 2024).
colorectal cancer (9 papers, 2017 to 2025). A primary or metastatic malignant neoplasm that affects the colon or rectum. "Ultimately, this study provides evidence on the molecular mechanism by which GSN and PRDX4 mediate an invasiveness pathway in colorectal cancer cells associated with the pathological stage IV lymph node-positive metastasis of CRC." (PMID 35804959, 2022). "Several previous studies reported that high expression of PRDX4 demonstrated an unfavorable prognosis in colorectal cancer, lung squamous cell carcinoma, oral cavity squamous cell carcinoma, and urinary bladder carcinoma." (PMID 30104402, 2018).
Sepsis (9 papers, 2011 to 2025). Sepsis is defined as life-threatening organ dysfunction caused by a dysregulated host response to infection. "Moreover, elevated serum PRDX4 protein levels are associated with poor outcomes and high mortalities in patients with sepsis." (PMID 31888585, 2019). "There were strong associations between sepsis events and the expression levels of GPX4 in classical and alternative monocytes, as well as PRDX4 in naïve CD4+ T cells and GR in naïve CD8+ T cells." (PMID 40593569, 2025). "PRDX2 deficiency as well as PRDX3 deficiency were increased LPS-induced septic shock in mice, and circulating PRDX4 level was reported as oxidative stress marker in patient with sepsis." (PMID 28881633, 2017). "High concentrations of PRDX4 are found in the blood of patients with sepsis and may reflect an antioxidant system in imbalance, like those with atherosclerosis." (PMID 36729923, 2023). "Indeed, Prdx4 levels in the serum of patients critically ill with sepsis and admitted to the ICU have been reported to be elevated as compared to control patients, and the levels of circulating Prdx4 correlate well with the severity of disease." (PMID 35052630, 2022).
gastric cancer (7 papers, 2011 to 2025). A primary or metastatic malignant neoplasm involving the stomach. "In cancers, PRDX4 is frequently overexpressed in multiple tumor types, including breast, prostate, ovarian, colorectal, lung, and gastric cancers, and is associated with tumorigenesis, therapeutic resistance, metastasis, and recurrence." (PMID 41373732, 2025). "A study has found that there is an interaction between PRDX4 and TXNDC5 protein molecules in gastric cancer, and PRDX4 may reduce lymphocyte infiltration, affect the expression of multiple immune checkpoints, leading to anti-tumor immune suppression." (PMID 41445793, 2025).
lung adenocarcinoma (7 papers, 2011 to 2025). A carcinoma that arises from the lung and is characterized by the presence of malignant glandular epithelial cells. "Weak PRDX4 expression in lung adenocarcinoma had a significantly close relationship with pathologically poor differentiation, highly invasive characteristics, and recurrence." (PMID 32903271, 2020). "Recently, we reported that peroxiredoxin 4 (PRDX4), an antioxidant enzyme, can be a prognostic marker of lung adenocarcinoma (LUAD)." (PMID 31588184, 2019). "The results showed that Prdx2 and Prdx4 were expressed higher in large cell lung carcinoma, lung adenocarcinoma, and squamous cell lung carcinoma compared with that in normal lung tissues." (PMID 30988280, 2019).
atherosclerosis (6 papers, 2019 to 2023). A disease characterized by the build-up of fatty material and calcium deposition in the arterial wall resulting in partial or complete occlusion of the arterial lumen. "Accordingly, PRDX4 is secreted in inflammation and it negatively regulates NF-кB signalling in atherosclerosis." (PMID 35456043, 2022). "In ApoE‒/‒ mice with transplanted bone marrow, hematopoietic Prdx4 overexpression was sufficient to suppress the progression of atherosclerosis." (PMID 34439492, 2021). "The overexpression of human Prdx4 in ApoE‒/‒ mice highly attenuated the development of atherosclerosis by limiting the infiltration of T-lymphocytes, reducing the OS, and ameliorating necrosis." (PMID 34439492, 2021). "We previously generated human PRDX4-transgenic mice (Tg mice) using C57BL/6 mice and reported that PRDX4 may have a protective role against the progression of atherosclerosis and nonalcoholic fatty liver disease via its antioxidant effect." (PMID 31888585, 2019).
ovarian carcinoma (6 papers, 2011 to 2022). A malignant neoplasm originating from the surface ovarian epithelium. "Elevated PRDX4 mRNA expression was associated with a better PFS in grade II or III ovarian cancer patients." (PMID 30104402, 2018). "In comparison, we found that among the detected 10 ovarian cancer tissues, there were 8 cases of medium and 2 cases of low PRDX4 staining." (PMID 30104402, 2018). "The clinical stage results showed that high mRNA expression of PRDX4 was related to a positive OS in stages I and II ovarian cancer patients." (PMID 30104402, 2018). "Due to these rather contradictory results, further research regarding the role of PRDX4 in ovarian cancer is needed." (PMID 30104402, 2018). "In the current study, we investigated the prognostic value of PRDX4 in several sets of clinical data, including histology, grade, stage, and applied chemotherapy for 1816 ovarian cancer patients." (PMID 30104402, 2018). "Further studies need to be done to validate the prognostic values of PRDX2 and PRDX4 in ovarian cancer." (PMID 30104402, 2018). "In contrast, we found that PRDX2 and PRDX4 showed better PFS in all ovarian cancer patients treated with Platin, Taxol, and Taxol+Platin chemotherapy, implying that PRDX2 and PRDX4 predict better prognosis in ovarian cancer patients treated with these three chemotherapeutic drugs." (PMID 30104402, 2018). "However, until the initiation of the current study, there is limited data about the prognostic value of PRDX4 in ovarian cancer." (PMID 30104402, 2018). "Additionally, increased expression of PRDX4 was associated with a positive OS in stages I and II patients and a better PFS in grade II or III patients, stages III and IV ovarian cancer patients." (PMID 30104402, 2018). "However, the use of PRDX1, PRDX2, and PRDX4 as a prognostic indicator in ovarian cancer needs further study." (PMID 30104402, 2018). "In addition, PRDX4 predicted better PFS in all ovarian cancer patients, serous ovarian cancer patients, and endometrioid cancer patients." (PMID 30104402, 2018). "However, the prognostic value of PRDX1, PRDX2, and PRDX4 in ovarian cancer requires further exploration." (PMID 30104402, 2018). "Our results showed that high PRDX4 level was related to a favorable OS for endometrioid cancer patients and a better PFS for all ovarian cancer patients, serous cancer patients, and endometrioid cancer patients." (PMID 30104402, 2018). "However, by comparing with public HPA database, we discovered that PRDX4 was significantly up-regulated at the protein levels in ovarian cancer tissues than that in normal ovarian tissues, implying that PRDX4 may play an essential role in the development of ovarian cancer." (PMID 30104402, 2018). "Furthermore, PRDX4 also predicted a better PFS in stages III and IV ovarian cancer patients, while PRDX4 presented a poorer OS in stages III and IV ovarian cancer patients." (PMID 30104402, 2018).
acute promyelocytic leukemia (5 papers, 2011 to 2022). An aggressive form of acute myeloid leukemia (AML), characterized by arrest of leukocyte differentiation at the promyelocyte stage, due to a specific chromosomal translocation t(15;17) in myeloid cells. "Prdx4 was downregulated in acute promyelocytic leukemia and Prdx3 overoxidization was reported in ageing; moreover, Prdx3 was found to be downregulated in cells from Fanconi anaemia (FA-G)." (PMID 24876913, 2014). "However, we find a strong reduction in PRDX4 expression levels in acute promyelocytic leukemia (APL) compared to normal promyelocytes and different molecular subtypes of AML." (PMID 21283726, 2011).
colitis (5 papers, 2020 to 2024). Inflammation of the colon. "In PRDX4-knockout mice, marked body weight loss and oxidative damage were observed in a dextran sulphate sodium-induced colitis model." (PMID 39683652, 2024).
idiopathic pulmonary fibrosis (5 papers, 2019 to 2023). Idiopathic pulmonary fibrosis (IPF) is a nonneoplastic pulmonary disease that is characterized by the formation of scar tissue within the lungs in the absence of any known cause. "Our recent study demonstrated that PRDX4 overexpression was associated with the aggravation of inflammation in idiopathic pulmonary fibrosis." (PMID 33456675, 2020). "PRDX4 is emerging as an important therapeutic target in numerous diseases, such as metabolic syndromes, idiopathic pulmonary fibrosis (IPF), liver injury, amyloid-beta aggregate-induced neuronal apoptosis." (PMID 33895140, 2021). "Moreover, as an animal model of pulmonary fibrosis, wild-type (WT) and PRDX4-transgenic (Tg) mice were intratracheally administered with bleomycin (BLM, 2 mg/kg), and fibrotic and inflammatory changes in lungs were evaluated 3 weeks after the intratracheal administration." (PMID 31888585, 2019). "Some scholars have stated that overexpression of PRDX4 does not show antioxidation, but induces inflammation and aggravates the development of pulmonary fibrosis." (PMID 36312597, 2022).
lymph node metastasis (5 papers, 2022 to 2025). "In addition to physiological functions, PRDX4 is also involved in therapeutic resistance, metastasis, and recurrence of tumors; its high expression is associated with the depth of invasion, lymph node metastasis, and short survival time." (PMID 35804959, 2022). "Identifying lymph node metastasis (LNM)-associated proteins by two-dimensional difference gel electrophoresis MS/MS in colorectal cells (CRC) indicates the reliability of candidate markers of GSN and PRDX4 and therapeutic targets for CRC." (PMID 35804959, 2022). "Moreover, we also found that PRDX4 was associated with multiple clinical characteristics, including age, sex, pathological subtype, lymph node metastasis, etc., suggesting that PRDX4 may be a potential prognostic marker for COAD." (PMID 36969053, 2023). "In all stages of lymph node metastasis, the mRNA expression of PRDX2, PRDX4, and PRDX6 was higher in LUAD samples than in normal samples." (PMID 40303499, 2025).
oral cavity squamous cell carcinoma (4 papers, 2018 to 2022). A squamous cell carcinoma arising from the oral cavity. "PRDX4 is a metastasis-related marker in oral squamous cell carcinoma, and high PRDX5 expression correlates with a poor prognosis." (PMID 35350568, 2022). "PRDX4 has been reported to promote progression of oral squamous cell carcinoma; however, the biological role of PRDX5 in HNSCC is unknown." (PMID 35350568, 2022).
Stroke (4 papers, 2017 to 2025). Sudden impairment of blood flow to a part of the brain due to occlusion or rupture of an artery to the brain. "The gene expression of PRDX1 and PRDX4 was elevated on day 7 in the hemisphere affected by stroke in comparison with the contralateral hemisphere and compared to day 3 (p < 0.05)." (PMID 40332314, 2025). "In vitro experiments using cultured oligodendrocytes and Prdx4 antibodies confirmed that the ability of LIF to reduce oxidative damage to white matter during stroke is primarily dependent upon its upregulation of Prdx4 through PI3K/Akt signaling." (PMID 26746670, 2017).
bladder cancer (3 papers, 2014 to 2018). "Evidence for OS and NS hallmarks in bladder cancer was provided by excess oxidative DNA damage (8-OHdG), 3-NT, and by peroxiredoxin 4 (Prdx4) upregulation that were associated with poor prognosis." (PMID 24876913, 2014). "The mitochondrial peroxidases, Prdx3 and Prdx4, were found to display expression changes in bladder cancer that related to disease prognosis, and Prdx3 upregulation was associated with increased cervical cancer risk; H2O2-induced Prdx3 overexpression was observed in the eye lens in cataractogenesis." (PMID 24876913, 2014).
Hyperglycemia (3 papers, 2014 to 2025). An increased concentration of glucose in the blood. "PRDX4 deficiency exacerbated neurodegeneration in the retina under hyperglycemia." (PMID 39706273, 2024). "In conclusion, our study suggested that PRDX4 reduces Müller cell apoptosis, alleviates reactive gliosis, maintains ER homeostasis, restores mitochondrial function, and suppresses oxidative stress of Müller cells under hyperglycemia, which is a potential protective mechanism in DR." (PMID 39706273, 2024). "In PRDX4-knockout (PRDX4-KO) mice, STZ-induced hyperglycemia resulted in significant retinal neurodegeneration, evidenced by reduced retinal thickness, increased apoptosis in the ganglion cell layer, elevated GFAP, and decreased glutamine synthetase." (PMID 40072104, 2025).
liver steatosis (3 papers, 2018 to 2020). "Prdx4 and superoxide dismutase 1 (Sod1) double-knockout mice (Prdx4−/y;Sod−/−) show more severe liver phenotypes, such as aggravated liver steatosis and liver failure, at a relatively young age compared with those of wild-type, Prdx4−/y, and Sod−/−." (PMID 32098329, 2020). "Several evidences outline a role of PRDXs in the modulation of hepatic functions: PRDX1 expression was decreased in the liver of HFD-fed mice, PRDX4 transgenic mice were resistant to hepatic steatosis, and insulin resistance increased in response to HFD." (PMID 31949886, 2019). "Thus, it is assumed that Prdx4 has a protective role against hepatic disorders by reducing oxidative stress and synergistically suppressing liver steatosis and inflammation in livers." (PMID 30050648, 2018). "The findings reported here indicate that, although the deletion of the Prdx4 gene alone had little effect on liver physiology, the deletion of Sod1 together with Prdx4 resulted in an enhanced level of aggravated liver damage compared to Sod1−/− mice, which reportedly develop liver steatosis." (PMID 30050648, 2018).
lung squamous cell carcinoma (3 papers, 2018 to 2022). "Furthermore, another study revealed that the expression of PRDX4 is closely related to the disease-free survival time and short recurrence time of patients with early-stage lung squamous cell carcinoma undergoing early radical surgery." (PMID 35308531, 2022).
Testicular atrophy (3 papers, 2017 to 2023). Wasting (atrophy) of the testicle (the male gonad) manifested by a decrease in size and potentially by a loss of fertility. "In our previous study, PRDX4 knockout mice displayed testicular atrophy with an increase in cell death due to oxidative stress." (PMID 28584396, 2017). "As of this writing, Prdx4−/y mice have shown no signs of tissue damage or abnormalities, except for testicular atrophy, and hence liver damage, if any, is latent in them." (PMID 30050648, 2018).
anaplastic thyroid cancer (2 papers, 2015 to 2022). "PRDX1, PRDX2, and PRDX3 expressions downregulated in papillary and anaplastic thyroid cancers, PRDX4 mRNA expression was moderately increased in anaplastic thyroid cancer tissues, and PRDX6 expression status showed similar levels as well as normal thyroid and thyroid cancers." (PMID 35571253, 2022). "PRDX1, PRDX2, and PRDX3 mRNA synthesis decreased in papillary and anaplastic thyroid cancers, PRDX4 mRNA expression was moderately increased in anaplastic thyroid cancer tissues, and PRDX6 expression status was at similar levels in normal thyroid and thyroid cancers." (PMID 26664298, 2015).
colon cancer (2 papers, 2023). "Based on the degree of staining, the protein expression of PRDX2 and PRDX4 was significantly higher in colon cancer tissues than in normal tissues." (PMID 36969053, 2023).
endothelial dysfunction (2 papers, 2019 to 2023). In vascular diseases, endothelial dysfunction is a systemic pathological state of the endothelium (the inner lining of blood vessels) and can be broadly defined as an imbalance between vasodilating and vasoconstricting substances produced by (or acting on) the endothelium. "If an exercise-induced improvement of TAG regulation and endothelial dysfunction was caused by an improvement in oxidative stress, then both PRDX4 and SOD3 would have decreased in the exercise versus control trial for both studies." (PMID 36729923, 2023).